EFS (embryonal Fyn-associated substrate)
Description:
Docking protein which plays a central coordinating role for tyrosine-kinase-based signaling related to cell adhesion. May serve as an activator of SRC and a downstream effector. Interacts with the SH3 domain of FYN and with CRK, SRC, and YES (By similarity).
Synonyms: hEFS; CASS3; EFS2; EFS1; SIN; CAS3
Tractability: Antibody: its Gene Ontology location is reachable by antibodies, with medium confidence.
Gene: Protein-coding gene on chromosome 14 (23,353,248 to 23,366,286, reverse strand). Ensembl gene ENSG00000100842.
Subcellular location (Human Protein Atlas): Nucleoplasm; Cytosol
Gene Ontology:
Molecular function: protein binding; protein domain specific binding; SH3 domain binding
Biological process: cell migration; cell surface receptor protein tyrosine kinase signaling pathway; intracellular signal transduction
Cellular component: cytoplasm; focal adhesion; plasma membrane
Genetic constraint (gnomAD): Loss-of-function variants: 34 observed, 38.85 expected, observed/expected ratio (o/e) 0.88, 90% interval 0.67 to 1.16. The upper end of that interval is the gene's LOEUF score, 1.16, which puts it in group 5 of 6, group 1 being the genes least tolerant of losing a copy. Missense variants: 715 observed, 686.42 expected, observed/expected ratio (o/e) 1.04, 90% interval 0.98 to 1.11. Synonymous variants: 296 observed, 294.34 expected, observed/expected ratio (o/e) 1.01, 90% interval 0.91 to 1.11.
Homologues: Orthologues: chimpanzee EFS (99% identical), macaque EFS (95% identical), dog EFS (88% identical), pig EFS (87% identical), rabbit EFS (86% identical), guinea pig EFS (84% identical), rat Efs (81% identical), mouse Efs (81% identical), zebrafish efs (40% identical), tropical clawed frog efs (29% identical), Drosophila melanogaster p130CAS (23% identical). Paralogues in human: BCAR1 (33% identical), NEDD9 (30% identical), CASS4 (19% identical).
Diseases named in the same sentence as EFS in open-access papers:
EFS is named in the same sentence as 58 diseases in open-access papers, as found by Europe PMC text mining. Sharing a sentence is not in itself a finding about the gene and the disease. The quoted sentences say what the papers report.
Hypertension (2 papers, 2009 to 2021). The presence of chronic increased pressure in the systemic arterial system. "Other putative off-targets such as ubiquinol-cytochrome-c reductases, globin-like proteins, EF hand-like calcium binding proteins (EFs), and LPTP are also directly or indirectly associated with hypertension, inflammation, and/or cancer." (PMID 19436720, 2009).
prostate tumor (1 paper, 2023). "SPP1 and CLDN8 were upregulated in prostate tumor tissues, whereas COL4A6, RND3, DPT, EFS, and TGFB1I1 were downregulated." (PMID 37251946, 2023).
cancer (22 papers, 2009 to 2025). A tumor composed of atypical neoplastic, often pleomorphic cells that invade other tissues. "Moreover, EFS protein acts as a scaffolding protein for cell signaling in the immune system and altered EFS expression was associated with cancer development." (PMID 34012728, 2021).
EFS also shares sentences with these, for which no sentence is quoted: infection (23 papers); tumor (17); breast cancer (12); lung carcinoma (5); glioma (4); cervical cancer (3); colon carcinoma (3); diabetes (3); Hyperglycemia (3); melanoma (3); asthma (2); bladder cancer (2); Duchenne muscular dystrophy (2); hepatocellular carcinoma (2); Insulin resistance (2); lung adenocarcinoma (2); neuroblastoma (2); Stroke (2); viral infection (2); ZIKV infection (2); Acidosis (1); acute T cell leukemia (1); adenocarcinoma (1); Allergy (1); alveolitis (1); Anxiety (1); bacterial infection (1); brain tumor (1); cognitive deficits (1); colorectal cancer (1).
A further 25 diseases each share a sentence with EFS in 1 paper.